H19 (H19 imprinted maternally expressed transcript)
Diseases named in the same sentence as H19 in open-access papers (continued):
Sharing a sentence is not in itself a finding about the gene and the disease.
diabetic cardiomyopathy (13 papers, 2016 to 2025). Diabetic cardiomyopathy is a disorder of the heart muscle in people with diabetes. "The present study was aimed to explore the pathogenic role of H19 in the development of diabetic cardiomyopathy." (PMID 27903964, 2017). "Our data, for the first time, reveal that the lncRNA H19/miR-29c/MAPK axis plays a pivotal role in the anti-apoptotic effect of melatonin in diabetic cardiomyopathy." (PMID 35890121, 2022). "In diabetic cardiomyopathy, cytosolic H19 forms miR-675-3p and miR-675-5p and attenuates apoptosis of CMs." (PMID 34604357, 2021). "In the rat model of diabetic cardiomyopathy, overexpression of H19 can attenuate apoptosis of diabetic CMs and improve left ventricular function, whereas knockdown of H19 shows opposite functions." (PMID 34604357, 2021). "Mechanistically, H19 expression is significant downregulated in the hearts of rats with diabetic cardiomyopathy, which leads to a reduced level of miR-675 and an increased level of miR-675 target-gene VDAC1." (PMID 34604357, 2021). "H19 is a primary miRNA precursor for microRNA-675 (miR-675) and the H19/miR-675 axis has been found in multiple biological processes, such as diabetic cardiomyopathy and tumorigenesis." (PMID 32434960, 2020). "Though the up-regulation of H19 has been reported in numerous tissues/cells in oxidative stress; studies have also shown the down-regulation of this lncRNA in rat models of diabetic cardiomyopathy (DCM)." (PMID 33381452, 2020). "In the previous study, we investigated the pathological roles of H19 in the development of diabetic cardiomyopathy." (PMID 31240820, 2019). "We previously generated a rat model of diabetic cardiomyopathy and found that the expression of long non-coding RNA H19 was downregulated." (PMID 27903964, 2017). "Therefore, H19 exerts a key role in the progression of diabetic cardiomyopathy by the reduction of ERS and thus in the subsequent derived apoptosis." (PMID 37373035, 2023). "In our previous studies, several ncRNAs including MIAT, MALAT1, H19 and circHIPK3 have been suggested to participate in the modulation of cardiomyocyte apoptosis and autophagy and consequently result in the development of diabetic cardiomyopathy." (PMID 31240820, 2019). "Thus, H19 is involved in the modulation of autophagy in diabetic cardiomyopathy by epigenetically silencing of DIRAS3." (PMID 31240820, 2019). "In the same way, in other cardiovascular pathologies such as atherosclerosis, cardiac hypertrophy, heart failure and dilated or diabetic cardiomyopathy, lncRNAs HypERlnc, NRB2, AC061961.2 and H19 exert different functions in the progression of these diseases." (PMID 37373035, 2023). "We previously established a rat model of diabetic cardiomyopathy (DCM) and found that the expression of lncRNA H19 was significantly downregulated." (PMID 27796346, 2016). "In conclusion, our study suggested that H19 could inhibit autophagy in cardiomyocytes by epigenetically silencing of DIRAS3, which might provide novel insights into understanding the molecular mechanisms of diabetic cardiomyopathy." (PMID 27903964, 2017).
gallbladder cancer (13 papers, 2016 to 2025). "Long non-coding RNA H19 regulates FOXM1 expression through competitively binding to endogenous miR-342-3p in gallbladder cancer." (PMID 37059588, 2023). "Our previous study found that H19 was over-expressed in gallbladder cancer (GBC) and was shown to promote tumor development in GBC." (PMID 27716361, 2016). "It has been reported that miR-342-3p was down-regulated to exert oncogenic roles in gallbladder cancer by H19, one of the earliest known lncRNAs, and miR-17-5p was also sequestered by H19, resulting in suppressing pro-proliferative mRNAs during myoblast differentiation." (PMID 38561330, 2024). "Moreover, overexpression of H19 in gallbladder cancer cells was shown to promote EMT and enhance cancer invasiveness by up-regulating the Twist-related protein 1 (Twist1)." (PMID 33402118, 2021). "Previous studies have shown that lncRNA H19 is upregulated and related to the cell proliferation and migration in a variety of cancers, including breast cancer, bladder cancer, pancreatic cancer, gallbladder cancer, and glioma." (PMID 27738631, 2016). "Gallbladder cancer development might be related to H19 and FAM30A." (PMID 35571069, 2022). "Based on the studies discussed in this review, H19 seems to induce drug resistance in ESCA, CRC, GC, and gallbladder cancer; however, it has a dual effect in promoting or inhibiting drug resistance in HCC, CCA, and PDAC." (PMID 33402118, 2021).
liver diseases (13 papers, 2017 to 2025). "H19 is the first lncRNA identified and characterized as the first imprinted gene in eukaryotes as a hepatic fetal-specific non-translatable mRNA in the late 1980s and has been implicated in various liver diseases." (PMID 36224648, 2022). "In order to develop future targets for therapies, it may be important to understand these mechanisms of 91H that have a direct effect on H19 expression, as well as 91H’s role in normal liver function, including its potential to cause liver disease." (PMID 28933364, 2017). "Further investigations are necessary to explore the underlying mechanism of STAT3-induced lncRNA-H19 expression and fully characterize the in vivo functions of lncRNA H19 during liver injury and other liver diseases." (PMID 32483425, 2020). "H19 participates in normal liver functions, such as development, and its dysregulation occurs in many liver disease, including HCC, type II DM, NAFLD, NASH, and cholestatic liver fibrosis." (PMID 28933364, 2017). "This review aims to further research utilizing H19 for drug discovery and the treatment of liver diseases by focusing on both the epigenetic regulation of H19 and how H19 regulates normal liver functions and diseases, particularly by epigenetic mechanisms." (PMID 28933364, 2017). "Interestingly, various lncRNAs, such as H19, HOTAIR, and MALAT-1, and their association with liver diseases have been highlighted as potential markers for disease progression or prognosis." (PMID 32157157, 2020). "Taken together, H19 plays a role in premalignant stages of liver disease." (PMID 32429417, 2020). "H19 was closely related to liver diseases and was up-regulated in human chronic liver diseases." (PMID 31064820, 2019). "Downregulation of H19, which was consistently observed in all most-DILI compounds except nimesulide, has been associated with formation of Mallory-Denk bodies (MDBs), aggresomes of proteins found in many types of liver diseases." (PMID 30515189, 2018). "Deregulation of H19 and MALAT1 has been associated with liver disease." (PMID 30515189, 2018). "Overall, we aim to provide a resource for future research on H19, so liver diseases may be treated more effectively in the future." (PMID 28933364, 2017). "Finally, we will explore using H19 in therapies for liver diseases either by targeting H19 or by directly using the H19 promoter to drive selective toxicity in cancer." (PMID 28933364, 2017). "A previous study in liver diseases showed that CTCF combines with maternal hypomethylation imprinting control region (ICR) to promote the expression of lncRNA H19, which is a regulator of fatty liver, fibrosis, and other liver diseases, suggesting that CTCF may play a role in NAFLD." (PMID 34566670, 2021). "This review will describe H19’s role in liver disease, including HCC, with a particular emphasis in any epigenetic regulation where H19 participates." (PMID 28933364, 2017).
gestational diabetes (12 papers, 2014 to 2025). Carbohydrate intolerance first diagnosed during pregnancy. "Furthermore, dysregulated expressions of several imprinted genes (e.g., Igf2, Phlda2, H19 and Gab1) in the placenta have been implicated in various pregnancy complications, including preeclampsia, gestational diabetes and FGR." (PMID 40550626, 2025). "Dysregulation of imprinted genes, including Igf2, Phlda2, H19 and Gab1 has been observed in placentas affected by pregnancy complications including preeclampsia, gestational diabetes and FGR." (PMID 40550626, 2025). "The expression of IGF2 is significantly higher in gestational diabetes mellitus, while the expression of H19 is significantly lower in GDM." (PMID 35563893, 2022). "In addition, modified expression of Igf2 and H19 genes was demonstrated in the sperm of adult F1 offspring of female mice with gestational diabetes." (PMID 28750655, 2017). "The study on gestational diabetes mellitus (GDM) mice showed that the pups demonstrated hypermethylation and epigenetic downregulation of IGF2 and H19 genes involved in insulin sensitivity." (PMID 37298715, 2023).
leukemia (12 papers, 2016 to 2024). A malignant (clonal) hematologic disorder, involving hematopoietic stem cells and characterized by the presence of primitive or atypical myeloid or lymphoid cells in the bone marrow and the blood. "The association between the H19 rs2839698 genotype and childhood leukemia was significant for survival time <5 years (adjusted OR = 1.43, 95%CI = 1.03–1.84), but not for those ≥5 years." (PMID 33800276, 2021). "In conclusion, our results reported for the first time that the variant genotypes and alleles of H19 rs2839698 were significantly associated with increased risks of childhood leukemia in Taiwan." (PMID 33800276, 2021). "Two hundred and sixty-six childhood leukemia patients and 266 healthy controls were enrolled in Taiwan, and two single nucleotide polymorphisms (SNPs), rs2839698 and rs217727, in H19 were genotyped and analyzed." (PMID 33800276, 2021). "H19 (3rd of the predictive list) was further confirmed to play critical roles in leukemia based on the observation that the loss of imprinting (LOI) of H19 was a frequent event in adult T-cell leukemia." (PMID 27517318, 2016). "The purpose of our study was to investigate whether genetic variations in lncRNA H19 were associated with susceptibility to childhood leukemia." (PMID 33800276, 2021). "We hypothesize that H19 rs2839698 and rs217727 SNPs may confer genetic susceptibility to childhood leukemia and thus conduct this case-control study to examine the association of these two SNPs with childhood leukemia in a Taiwan population." (PMID 33800276, 2021). "While H19 expression is increased in numerous leukemias and has both tumor-inducing and tumor maintenance roles, H19 has also been shown to promote and maintain the cancer stem cell phenotype." (PMID 38791169, 2024). "Our pilot study found CT and TT of H19 rs2839698 had a higher expression of H19 mRNA in serum than those with CC genotype among 30 childhood leukemia patients." (PMID 33800276, 2021). "For example, lncRNA H19 expression was significantly upregulated in bone marrow samples from leukemia patients, which regulated ID2 expression by competitive binding to hsa-miR-19a/b." (PMID 30925672, 2019). "We first identified the potential biological role of H19 in leukemia by bioinformatics analysis on the basis of Coremine Medical mining." (PMID 29643943, 2018). "H19 overexpression promotes leukemia and predicts poor prognosis in AML." (PMID 39758420, 2024). "H19 dysregulation is present in a large number of solid tumors and leukemia." (PMID 36680478, 2023). "Taken together, these results suggested that H19 played an oncogenic role in leukemia." (PMID 34421359, 2021). "Our current study is the first report of these two H19 SNPs in childhood leukemia." (PMID 33800276, 2021). "The axis of DDX43/H19/miR‐186 may be an attractive candidate for overcoming drug resistance in leukemia therapy." (PMID 30793488, 2019). "The investigations on H19 functions were more widely depicted in solid tumors than in leukemia." (PMID 29703210, 2018). "In summary, the signal of miR-186/DDX43/H19 may be involved in regulating the function of leukemia cells." (PMID 29449695, 2018). "Next, we performed in vitro experiments to validate the leukemia-promoting effects of H19 in AML." (PMID 29643943, 2018).
oral squamous cell carcinoma (12 papers, 2018 to 2024). "H19, a 2.3 kb lncRNA, has been linked to tumor metastasis and progression, but its significance in oral squamous cell carcinoma (OSCC) remains unclear." (PMID 39659621, 2024).
preeclampsia (12 papers, 2012 to 2025). Preeclampsia is a hypertensive disorder of pregnancy that is characterized by new-onset hypertension with proteinuria presenting after 20 weeks of gestation, and depending on mild or severe forms may initially present with severe headache, visual disturbances, and hyperreflexia. "Loss of H19 imprinting is suspected to be involved in the pathomechanism of preeclampsia and growth restriction during pregnancy." (PMID 33923632, 2021). "Intriguingly, biallelic expression of H19 in term placentae has been associated with preeclampsia in one study, yet subtle variation in H19 allelic expression in healthy term placentae has also been observed." (PMID 23227253, 2012). "H19 was expressed during the first trimester of pregnancy in women who later develop preeclampsia." (PMID 40870007, 2025). "As noncoding RNAs are an important part of evolutionary genetics and have been confirmed to play regulatory roles in preeclampsia, seven lncRNAs reported to be associated with hypoxia were selected, including UCA1, EFNA3, H19, MALAT1, HOTAIR, FALEC, and HAS2-AS1." (PMID 36160709, 2022). "Given the importance of PIF during embryonal/fetal development and the high expression of H19 during this period, the question whether the sPIF/H19 axis is active beyond oligodendrocyte modulation and the impact on preterm birth or preeclampsia remains to be investigated." (PMID 34676826, 2021). "Moreover, the dynamic profile of H19 expression may support normal pregnancy, while its impaired regulation might promote preeclampsia, early-onset preeclampsia (EOPE), and IUGR." (PMID 29954144, 2018). "Combining with H19, MALAT-1, MEG3 and so on, the involvement of lncRNAs in preeclampsia will become more clear." (PMID 32194641, 2020). "In conclusion, we identified that besides lncRNA H19, SPRY4-IT1 could also participate in the pathogenesis of preeclampsia." (PMID 24223182, 2013). "Taken together with our previous study reported significant lower methylation in offspring of preeclampsia than normal pregnancy, it indicates that the methylation of IGF2 DMR could be a better biomarker than H19 DMR to evaluated the effect of environmental exposure in early development." (PMID 25269528, 2014).
breast tumors (11 papers, 2012 to 2023). "H19 is one of the most studied lncRNAs involved in BC evolution, which is aberrantly upregulated in human breast tumor tissues and cells and associated with an increased risk of BC." (PMID 37568579, 2023). "For this, a meta-analysis on the gene expression data of more than 5000 breast tumor samples was first carried out to explore the correlation of H19 expression and that of the stem cell gene signature." (PMID 32610610, 2020). "Studies uniformly revealed that breast CSCs (BCSCs)-enriched populations and breast tumors show high H19 expression." (PMID 29299179, 2017). "To assess the clinical relevance of our findings, we examined the expression of H19 in 70 primary breast tumors that were obtained from postmenopausal women." (PMID 25944846, 2015). "In this context, H19 is an estrogen-regulated gene that was previously identified as a breast tumor oncogene." (PMID 25944846, 2015). "In agreement, H19 is significantly elevated in breast tumors and BCSC-enriched populations." (PMID 28102845, 2017). "In the present study, we used the sensitive and quantifiable qPCR assay to examine the expression of H19 in ER+ and ER− breast tumor samples that contained at least 70% tumor cells and found that H19 expression was highly correlated with ERα expression in these tumors." (PMID 25944846, 2015). "Lastly, we explored the clinical relevance of the estrogen–H19 signaling axis in breast tumors and found that ERα+ tumors exhibited a higher expression of H19 as compared with ERα− tumors and that H19 expression showed a positive correlation with ERα expression in those tumors." (PMID 25944846, 2015). "It was recently shown that a long non-coding RNA (lncRNA), that we named the 91H RNA (i.e. antisense H19 transcript), is overexpressed in human breast tumours and contributes in trans to the expression of the Insulin-like Growth Factor 2 (IGF2) gene on the paternal chromosome." (PMID 22662250, 2012). "Moreover, a previous study revealed that the dysregulation of H19 could facilitate breast tumor progression after the subcutaneous injection of H19-recombined cells into SCID mice." (PMID 29299179, 2017). "Here we demonstrate that H19 expression is enriched in BCSC subpopulations and breast tumor samples." (PMID 28102845, 2017). "Also, when the expression of H19 was examined in the ERα+ breast tumors, a strong positive correlation was obtained (r=0.763), whereas no such correlation was observed when H19 expression was examined against the ERαlow/− tumors (r=0.38)." (PMID 25944846, 2015).